PAQR9 (progestin and adipoQ receptor family member 9)
Description:
Plasma membrane progesterone (P4) receptor coupled to G proteins. Seems to act through a G(s) mediated pathway. May be involved in regulating rapid P4 signaling in the nervous system. Also binds dehydroepiandrosterone (DHEA), pregnanolone, pregnenolone and allopregnanolone.
Synonyms: FLJ41938; BLNC1
Tractability: Antibody: UniProt places it where antibodies can reach, with high confidence; UniProt predicts a signal peptide or a membrane-spanning region; its Gene Ontology location is reachable by antibodies, with medium confidence. PROTAC: its protein half-life has been measured.
Gene: Protein-coding gene on chromosome 3 (142,949,164 to 142,964,022, reverse strand). Ensembl gene ENSG00000188582.
Subcellular location: Cell membrane
Gene Ontology:
Molecular function: signaling receptor activity
Cellular component: membrane; plasma membrane
Genetic constraint (gnomAD): Loss-of-function variants: 12 observed, 23.58 expected, observed/expected ratio (o/e) 0.51, 90% interval 0.32 to 0.82. The upper end of that interval is the gene's LOEUF score, 0.82, which puts it in group 3 of 6, group 1 being the genes least tolerant of losing a copy. Missense variants: 418 observed, 525.57 expected, observed/expected ratio (o/e) 0.8, 90% interval 0.73 to 0.86. Synonymous variants: 266 observed, 241.59 expected, observed/expected ratio (o/e) 1.1, 90% interval 1 to 1.22.
Homologues: Orthologues: chimpanzee PAQR9 (100% identical), macaque PAQR9 (99% identical), guinea pig PAQR9 (94% identical), pig PAQR9 (94% identical), dog PAQR9 (94% identical), mouse Paqr9 (93% identical), rat Paqr9 (93% identical), rabbit PAQR9 (78% identical), tropical clawed frog paqr9 (69% identical), zebrafish paqr9 (34% identical). Paralogues in human: PAQR6 (27% identical), PAQR5 (22% identical), PAQR7 (20% identical), ADIPOR2 (19% identical), PAQR8 (17% identical), ADIPOR1 (16% identical), PAQR3 (16% identical), PAQR4 (14% identical), MMD2 (10% identical), MMD (8% identical).
Diseases named in the same sentence as PAQR9 in open-access papers:
PAQR9 is named in the same sentence as 16 diseases in open-access papers, as found by Europe PMC text mining. Sharing a sentence is not in itself a finding about the gene and the disease. The quoted sentences say what the papers report.
Insulin resistance (5 papers, 2018 to 2024). Increased resistance towards insulin, that is, diminished effectiveness of insulin in reducing blood glucose levels. "Overall, PAQR9 deficiency reverses statin‐induced hepatic insulin resistance and diabetes." (PMID 38970167, 2024). "As an energy sensor and lipid‐oxidative regulator in hepatocytes, PAQR9 is found to be upregulated by statin treatment, while Paqr9−/− mice exhibit ameliorated insulin resistance under statins or HFD." (PMID 38970167, 2024). "With the Paqr9−/− mice have been reported, we explored whether deletion of PAQR9 protected mice from atorvastatin‐induced hepatic insulin resistance." (PMID 38970167, 2024).
diabetes (2 papers, 2022 to 2024). "The interventions on PAQR9, including deletion of PAQR9, caloric restriction and HNF4α activation, are all effective treatments for statin‐induced diabetes, while liver specific over‐expression of PPM1α is another possible tactic." (PMID 38970167, 2024). "Above all, we demonstrated that different interventions on HNF4α‐PAQR9‐PPM1α pathways could be effective therapies for statin‐induced diabetes." (PMID 38970167, 2024). "We have also noticed the function of PAQR9 in regulating HFD‐induced diabetes and NAFLD, which might relate to its effect on lipid metabolism (unpublished observation)." (PMID 38970167, 2024).
schizophrenia (1 paper, 2017). A major psychotic disorder characterized by abnormalities in the perception or expression of reality. "These include: VAT‐1, DAD‐1, PAQR9, BCKD, BDH, Prickle4, PP2A, RPL13A, SPRED2, KLP, FAM36A, NAB1, CLSTN3, PEDF‐R, and FZD3 (Frizzled gene previously associated with different psychopathologies, most notably Schizophrenia)." (PMID 27696737, 2017).
cancer (2 papers, 2022 to 2024). A tumor composed of atypical neoplastic, often pleomorphic cells that invade other tissues. "By the way, according to the pathway, PAQR9 might play an anti‐cancer factor in the liver, which has been verified in our lab (unpublished observation)." (PMID 38970167, 2024). "High methylation levels of PAQR9 were observed in most cancers, especially in the COAD." (PMID 36518255, 2022).
tumor (1 paper, 2023). "Anatomical tumor recurrence between the lungs, liver, lymph nodes, bones, and brain revealed significant differential expression for CCM1, PAQR9, and PGRMC1, along with AFP, in HCC patients, while no significance was observed for CCA patients." (PMID 36980321, 2023).
PAQR9 also shares sentences with these, for which no sentence is quoted: Hepatic steatosis (8 papers); Obesity (5); breast carcinoma (1); diabetic nephropathy (1); dyslipidemia (1); Glucose intolerance (1); liver fibrosis (1); metabolic disorders (1); myopathies (1); nonalcoholic steatohepatitis (1); renal fibrosis (1).